GSK3B (glycogen synthase kinase 3 beta)
Diseases named in the same sentence as GSK3B in open-access papers (continued):
Sharing a sentence is not in itself a finding about the gene and the disease.
ischemia (52 papers, 2012 to 2025). A hypoperfusion of the BLOOD through an organ or tissue caused by a PATHOLOGIC CONSTRICTION or obstruction of its BLOOD VESSELS, or an absence of BLOOD CIRCULATION. "After ischemia onset, microglia are rapidly activated to the M1 type along with GSK-3β overactivation and thus secrete a variety of proinflammatory factors, such as TNF-α, IL-1, and IL-6, leading to an inflammatory cascade." (PMID 41292262, 2025). "GSK-3β is activated by ischemia through decreased activity of the phosphatidylinositol 3-kinase/Akt pathway." (PMID 36142419, 2022). "Inhibition of GSK-3β has also been confirmed to stimulate the mTOR pathway in the heart during ischemia/reperfusion." (PMID 34298987, 2021). "We intend to prove that electroacupuncture pretreatment by excited adenosine Α1 receptor induced phosphorylation of GSK-3β, thus improving the tolerance of nerve cells to ischemia." (PMID 32149120, 2020). "Numerous reports have declared that GSK-3β, involved in the regulation of differentiation, survival, activation, or over-expression are related to ischemia neuronal death during transient cerebral ischemia." (PMID 32351385, 2020). "And studies have shown that DEX has a good effect in the treatment of tissue ischemia-reperfusion injury, improving myocardial ischemia-reperfusion injury in DM patients by regulating the GSK-3β signaling pathway." (PMID 31886285, 2019). "Another report, however, did validate a GSK-3β inhibitor in an acute ischemia rat model, displaying reduced infarct volume, brain edema, and neurological deficit." (PMID 30079246, 2018). "Since Akt and GSK-3β regulate the myocardial apoptotic pathway, we evaluated Bax and Bcl-2 expression levels after ischemia/reperfusion." (PMID 27077846, 2016). "Different degrees of ischemia and various ischemia models generated via the Akt/GSK-3β pathway following cerebral ischemia show different disease states." (PMID 25187832, 2014). "GSK-3β is activated to promote apoptosis in 90-min focal cerebral ischemia models (severe ischemia)." (PMID 25187832, 2014). "In compatible with neurogenesis, DJS modulated ischemia-induced changes in Akt/GSK3β/β-catenin singaling." (PMID 24261472, 2013). "Direct inhibition of GSK-3β by the use of structurally different pharmacological inhibitors (SB-216763, LiCl) administered either before ischemia or reperfusion limits infarct size." (PMID 24288674, 2013). "Moreover, the increasing phosphorylation levels on Y216 (tyrosine 216) from GSK-3β was observed in degenerating cortical neurons induced by ischemia." (PMID 39125907, 2024). "These treatments prevented the decrease of phospho-Akt and phospho-GSK-3β levels induced by ischemia, reducing the ischemia-induced increase of phospho-DRP2 by “active” dephospho-GSK-3β, and improving the integrity and protection of axons/dendrites against ischemic injury." (PMID 37175950, 2023). "In addition, GSK-3β has been shown to catalyze the phosphorylation of tau protein through elevated α-synuclein as a result of ischemia, which is important for secondary brain damage after ischemia." (PMID 37686098, 2023). "Furthermore, it inhibits glycogen synthase kinase-3 beta (GSK3-β) activity in rats treated with it before ischemia." (PMID 36078175, 2022). "Certainly, pharmacologically inhibiting GSK-3β confer the possible therapeutic effects against renal injury in vivo in the rat model of ischemia and the murine models of endotoxemia and pharmacological stimulation, including nonsteroidal anti-inflammatory drug diclofenac and mercuric chloride." (PMID 34440091, 2021). "Activated GSK-3β is known to stimulate autophagy during ischemia whereas inactivation of GSK-3β inhibits autophagy during reperfusion, suggesting that the dephosphorylated state of GSK-3β has a cardioprotective role during the ischemic phase through upregulation of autophagy." (PMID 32121587, 2020). "Inhibition of GSK3β promotes the mitochondrial biogenesis during ischemia cerebral injury." (PMID 29636855, 2018).
ischemia (continued). "Furthermore, Issan and colleagues have demonstrated that pharmacological induction of HO-1 by CoPP protects H9c2 cells against hypoxia and also diabetic hearts from ischemia via the modulation of the AKT/GSK3β pathway." (PMID 29597322, 2018). "Inactivation of GSK-3β ameliorated ischemia-induced blood brain barrier (BBB) hyper-permeability." (PMID 28824887, 2017). "Studies have shown that ERS becomes prominent upon reperfusion but not during ischemia, while inhibition of ERS could protect the heart from ischemia reperfusion injury by modulation of the mPTP opening through inactivation of GSK-3β in vivo and in vitro." (PMID 29391923, 2017). "In our experimental model, the treatment with both GSK-3β inhibitors before and after ischemia exhibited exactly the same cardioprotective profile as PRE and POS, suggesting that the infarct-limiting effect of both interventions is linked in a cause-effect relationship to GSK-3β-dependent mechanism." (PMID 24288674, 2013). "In rodent and porcine models of ischemia–reperfusion injury, lithium administration before or during ischemia significantly reduces infarct size by preventing the opening of the mitochondrial permeability transition pore (mPTP), an event mediated by GSK-3β-dependent pathways." (PMID 40710791, 2025). "The augmented expression of p-Akt (ser473) and p-GSK-3β (ser9) occurred in severely damaged neurons localized in close proximity to the ischemic core indicating that the upregulation of both kinases is prominent in neurons in which the impact of ischemia is most pronounced." (PMID 33864097, 2021). "Thus, IGF-1/GSK-3β signaling might be critical for ischemia-induced neuronal hyperproliferation in the hippocampal dentate gyrus region." (PMID 27866373, 2017). "In particular, our study highlights the importance of PI3K-Akt-GSK3β and eNOS pathways in the cardioprotective role of Cst, underlining its function in the stabilization of MMP and in the modulation of calcium signaling within cardiac cells undergoing ischemia and reperfusion." (PMID 25774921, 2015). "Activation of the AKT/GSK3β signaling pathway, demonstrated as increases in the levels of P-AKT(ser473) and P-GSK3β(ser9), has been reported to protect against myocardial apoptosis induced by ischemia/reperfusion in rats and to increase the survival of hippocampal neurons following ischemia in rats." (PMID 24580743, 2014). "Therefore any strategy to activate PI3K/Akt and associated GSK-3β pathway to release the diabetic inhibition of both IPC and Ipost-mediated myocardial protection may provide the protective effect against ischemia/reperfusion injuries." (PMID 21822424, 2012). "Our data would be consistent with reduced GSK3β and/or enhanced PKA signaling that have been reported during ischemia." (PMID 37949223, 2023). "From these observations we propose that PKG1α gene delivery promotes the myogenic potential of MSCs by phosphorylating and inactivating GSK3β activity via PI3K/Akt pathway and contributing to the cardiac recovery after ischemia." (PMID 23536905, 2013). "On the other hand, the period of ischemia (10 min) used for the protocol of ischemia reperfusion by these authors would be comparable to our PRE protocol, in which inactivation of GSK-3β was obtained." (PMID 24288674, 2013). "In addition, miR-29a-5p agomir treatment suppressed the increasing expression of GSK3β, FKBP5, and AQP4 in the peri-infarction tissue compared with the ischemia-reperfusion group (p < 0.001), as shown by Western blot analysis." (PMID 40529227, 2025). "Consistent with other studies showing that GSK-3 is involved in several nephrotoxicity models, including endotoxemia, ischemia, and non-cisplatin drugs, this study also provides evidence of cisplatin-induced GSK-3β activation in vivo and in vitro." (PMID 34440091, 2021). "One hypothesis is that ischemia may activate CDK-5 and GSK-3β, resulting in tau phosphorylation." (PMID 36142419, 2022).
ischemia (continued). "Active GSK-3β is not enhanced in ischemia models, and Nrf2 downregulated as a consequence." (PMID 30079246, 2018). "Here, we found out that high expression of GSK-3β and suppression of PP2A were evoked by ischemia damage but regulated by acupuncture treatment in vivo, which suggests that mechanism of acupuncture neuroprotection may be associated with regulation GSK-3β and PP2A expression." (PMID 25120577, 2014). "Changes in GSK3β activity occur after cerebral ischemia in regional, severity of injury, or model dependent manner: increase in cortical and striatal neurons after global ischemia; decreases in the hippocampal CA1 but not CA3 region after global ischemia." (PMID 24261472, 2013). "The ratio of GSK-3β and PP2A was also dramatically elevated post-ischemia, but decreased in no-acupuncture group and acupuncture group (P < 0.05)." (PMID 25120577, 2014).
non-small cell lung carcinoma (52 papers, 2013 to 2026). A group of at least three distinct histological types of lung cancer, including non-small cell squamous cell carcinoma, adenocarcinoma, and large cell carcinoma. "In contrast, UBE2L3, associated with the SCF ubiquitin ligase complex, promotes non-small cell lung cancer by ubiquitinating and degrading p27kip1 and glycogen synthase kinase 3β (GSK-3β)." (PMID 38226814, 2024). "Among them, Nobiletin was reported to enhance chemosensitivity to adriamycin by modulating the Akt/GSK3β/β-Catenin/MYCN/MRP1 signalling pathway in A549 human non-small cell lung cancer cells." (PMID 41579221, 2026). "GSK3B inhibitors also worked synergistically with paclitaxel to suppress non-small cell lung cancer (NSCLC) cells." (PMID 39166606, 2024). "Astragaloside IV, an active ingredient in Astragalus membranaceus, inhibited non-small cell lung cancer development via inhibition of the Akt/GSK-3β/β-catenin signaling axis, resulting in the induction of apoptosis." (PMID 37047425, 2023). "Excitingly, the protein levels of GSK3B were significantly downregulated after 24 h of treatment of non-small-cell lung cancer H1299 and A549 with the indicated concentrations of triptonodiol." (PMID 38017514, 2023). "The protein abundance of GSK3B was significantly downregulated in non-small-cell lung cancer cells H1299 and A549 treated with triptonodiol for 24 h." (PMID 38017514, 2023). "Taken together, we considered that the apoptosis effect of CTT on non-small cell lung cancer is related to the pathway of PI3K/AKT/GSK3B, and that the apoptosis effect of the previously known CTT needs to be compared with conventional chemotherapy." (PMID 30217003, 2018). "The relationship between WIF-1, Gsk-3β and nm23-H1 expression and the prognosis in patient with non-small cell lung cancer." (PMID 27911280, 2017). "For example, in non-small cell lung cancer (NSCLC), GSK-3β expression is associated with cervical lymph node metastases, poor differentiation, advanced stage, late diagnosis, and worse survival, while inhibiting GSK-3 can result in cancer cell apoptosis and cell cycle arrest." (PMID 35911672, 2022). "GSK3β has been shown to be significantly increased in non-small cell lung cancer patient samples with increased expression correlated with a poor long-term prognosis, and GSK3β was also shown to have inconsistent effects on Wnt/ β-catenin signalling depending on cell-type." (PMID 34739494, 2021). "For example, AS-IV could inhibit the migration and proliferation of non-small cell lung cancer (NSCLC) cells and caused a noticeable increase in cell death via inhibition of the Akt/GSK-3β/β-catenin signaling axis." (PMID 30909474, 2019). "Therefore, to explore potential isoform-specific functions of Dyn1 and Dyn2, as well as the role of GSK3β in regulating Dyn1 activity, we generated genome-edited H1299 non-small cell lung cancer cells, which we previously showed partially utilize Dyn1 for CME." (PMID 29668686, 2018). "In prostate cancer, it enhances tumor progression by stabilizing androgen receptors through MYLIP interaction, and in non-small-cell lung cancer, it contributes to chemoresistance and metastasis through NF-κB and AKT/GSK3β signaling." (PMID 40001982, 2025). "This induced the activation of PI3K/AKT/GSK3β/β-catenin signaling, which in turn, induced EMT and metastasis of non-small cell lung cancer (NSCLC) cells." (PMID 31027222, 2019). "In non-small cell lung cancer (NSCLC) cells, the ectopic expression of Spns2, an S1P transporter, resulted in increased apoptosis through modulation of GSK-3β and Stat3 pathways." (PMID 28352271, 2017). "Moreover, tyrosine kinase inhibitors (TKIs) give rise to GSK3β-dependent phosphorylation of MCL-1, translocation of MCL-1 to nucleus, as well as FBXW7-mediated degradation through targeting PI3K/AKT signaling, which overcome the resistance to targeted therapy in non-small cell lung cancer (NSCLC)." (PMID 35515121, 2022).
non-small cell lung carcinoma (continued). "However, other study indicated that LiCl significantly enhanced cell apoptosis in non-small cell lung cancer by upregulating the death receptors DR4 and DR5, and LiCl sensitized cells to TRAIL-induced apoptosis independent of GSK3β." (PMID 33557839, 2021).
Cerebral ischemia (49 papers, 2012 to 2026). Restriction of arterial blood supply to the brain associated with insufficient oxygenation to support the metabolic requirements of the tissue. "A recent study verified that GSK-3β downregulates expression of NRF2 protein and genes downstream of NRF2/ARE in brain ischemia–reperfusion injury, suggesting that GSK-3β is a negative regulatory of NRF2 and the associated antioxidant response." (PMID 31387531, 2019). "It is noteworthy that the PI3-K/Akt-dependent GSK-3β signaling pathway was involved in the expression of NeuroD, which underlies cerebral ischemia-induced neurogenesis." (PMID 27866373, 2017). "Our results suggest that this PI3-K-dependent Akt/GSK-3β/β-catenin signaling pathway was, at least in part, associated with the expression of NeuroD after severe cerebral ischemia." (PMID 27866373, 2017). "In this study, Akt phosphorylation at Ser473 and GSK-3β dephosphorylation at tyr216 were increased in warfarin-associated HT after cerebral ischemia." (PMID 27566245, 2016). "We observed that Ex-4 ameliorated warfarin-associated HT and preserved the integrity of the BBB after cerebral ischemia through the PI3K/Akt/GSK-3β pathway." (PMID 27566245, 2016). "In the model of warfarin-associated HT after cerebral ischemia, GSK-3β knockdown by siRNA significantly prevented the warfarin-induced BBB disruption." (PMID 27566245, 2016). "Herein, we hypothesized that Ex-4 would stabilize the BBB and suppress neuroinflammation through PI3K-Akt-induced inhibition of GSK-3β after warfarin-associated HT post-cerebral ischemia in mice." (PMID 27566245, 2016). "Therefore, we hypothesized that Ex-4 would stabilize the blood-brain barrier (BBB) and suppress neuroinflammation through PI3K-Akt-induced inhibition of glycogen synthase kinase-3β (GSK-3β) after warfarin-associated HT post-cerebral ischemia." (PMID 27566245, 2016). "ACEA treatment promotes the phosphorylation of GSK-3β, enhancing mitochondrial biogenesis and providing a protective response to brain ischemia." (PMID 39707578, 2024). "Sevoflurane preconditioning can protect against cerebral ischemia by increasing the anti-inflammatory phenotype of microglia through activating the GSK-3β/NRF2 pathway." (PMID 37361996, 2023). "We and others demonstrated that PI3-K/Akt/GSK-3β signaling in neural stem cells is involved in neurogenesis in response to cerebral ischemia." (PMID 35216064, 2022). "The PI3K/Akt/GSK-3β signaling pathway plays crucial roles in neuroprotection against cerebral ischemia injury." (PMID 35814200, 2022). "The PI3K/Akt/GSK-3β signaling pathway is one of the crucial signaling pathways and therapeutic targets for neuroprotection against cerebral ischemia injury." (PMID 35814200, 2022). "Recent studies have focused on modulating Nrf2 by GSK-3β to counter the altered oxidative environment of brain tissues after cerebral ischemia." (PMID 36139821, 2022). "A number of studies have indicated that inhibition of GSK-3β ameliorated cerebral ischemia injury, consistent with our findings." (PMID 33935731, 2021). "Cerebral ischemia for 1.5 h followed by 24 h of reperfusion downregulated the ratio of p-GSK-3β(Ser9)/GSK-3β, and markedly upregulated HO-1 expression in the rat infarct tissue." (PMID 33935731, 2021). "A number of studies have indicated that inhibition of GSK-3β contributed to an amelioration of cerebral ischemia injury, which is consistent with our findings." (PMID 33935731, 2021). "The relationship between GSK-3β and HO-1 pathway in the process of cerebral ischemia is shown as follows: significant amounts of oxidants are generated during cerebral ischemia/reperfusion, and oxidative stress causes brain damage after stroke." (PMID 33935731, 2021). "Maslinic acid found in Olea europaea species, for instance, induces synaptogenesis and axonal regeneration in cerebral ischemia model though the regulation of Akt/GSK-3β signaling pathway." (PMID 33251156, 2020).